KRT19 (keratin 19)
Diseases named in the same sentence as KRT19 in open-access papers (continued):
Sharing a sentence is not in itself a finding about the gene and the disease.
cholangiocarcinoma (58 papers, 2012 to 2026). A carcinoma that arises from the intrahepatic biliary tree (intrahepatic cholangiocarcinoma) or from the junction, or adjacent to the junction, of the right and left hepatic ducts (hilar cholangiocarcinoma). "The two cell lines also expressed Krt19, a marker typically associated with cholangiocarcinoma, which is a recognized finding in highly aggressive HCCs with poor prognosis." (PMID 39051113, 2024). "The findings indicated that the levels of the genes reported as phenotypic markers for cholangiocarcinoma, including Epcam, Kit, Krt7, Krt19, and Muc1, were upregulated, suggesting that the cancerous lesions in the liver appeared to be cholangiocarcinoma." (PMID 37834032, 2023). "Having been extensively reported in the literature as a specific marker for malignant cells in ICC, KRT19 was highly expressed in the right regions of the pathological image, indicating that these regions were affected by cholangiocarcinoma." (PMID 37401015, 2023). "KRT19 expression was confirmed in the intracellular cholangiocarcinoma-like lesions by immunohistochemical staining." (PMID 34158541, 2021). "AFP positive regenerative nodules were frequently seen in Pemt−/− mice fed HFHS and cytokeratin 19 positive cholangiocellular carcinoma developed in ~10% of Pemt−/− mice fed HFHS." (PMID 26883167, 2016). "In the present study, RKIP and cytokeratin 19 expression was detected in the extrahepatic tissues of cholangiocarcinoma patients by immunohistochemistry." (PMID 25435928, 2015). "Cytokeratin 19, for example, is useful to differentiate cholangiocarcinoma from HCC, but its positivity is similar between cholangiocarcinoma and gastrointestinal adenocarcinoma." (PMID 33852640, 2021). "Carbohydrate antigen 19-9 (CA19-9), leucine-rich α2-glycoprotein (LRG1), interleukin 6 (IL6), pyruvate kinase M2 (PKM2), cytokeratin 19 fragment (CYFRA21.1) and mucin 5AC (MUC5AC) have reported utility for differentiating cholangiocarcinoma (CCA) from benign biliary disease." (PMID 29707118, 2018). "However, staining for cytokeratin 19 (CK19), a biomarker for cholangiocarcinoma, was negative." (PMID 32296582, 2020).
pancreatic cancer (51 papers, 2006 to 2025). "We found that the expression of genes characteristic of early stem cells, NANOG (p = 0.03), and the expression of genes encoding insulin and cytokeratin 19 (INS p = 0.02, CK19 p = 0.005) were increased in pancreatic cancer patients." (PMID 40699634, 2025). "KRT19 is also proven to participate in immune evasion and is associated with poor prognosis in pancreatic cancer." (PMID 36522691, 2022). "Consistent with our study, several studies have reported increased CSTB, MIF, and KRT19 levels in pancreatic cancer." (PMID 40289610, 2025). "Common markers, such as Acta2, Mki67 and Krt19, were expressed in specific subpopulations, confirming the pancreatic cancer cell identity." (PMID 40621620, 2025). "In summary, our single-cell RNA sequencing and bioinformatics analysis identified several highly variable genes including IFI27, KRT18, KRT19, MMP1, MMP3, and NEFL, whose expression is associated with a shorter overall survival of pancreatic cancer patients." (PMID 36010660, 2022). "Cyfra 21-1, a soluble fragment of KRT19, has already been shown to be a useful serum biomarker in lung, esophageal, breast, colorectal, ovarian, and pancreatic cancers." (PMID 34944713, 2021). "The coexpression of pancreatic cancer-enriched cytokeratins (Krt7 and Krt19) in single cells expressing these ECM gene products excludes the possibility that these represent circulating tumor-derived fibroblasts." (PMID 25242334, 2014). "We determined the genes that express differently in pancreatic cancer tissues compared with normal tissues and associate with survival (P < 0.05) as Hub genes, yielding a total of six Hub genes, including S100A14, KRT8, KRT19, MAL2, MYO5B, and PSCA." (PMID 36522691, 2022). "We analyzed the infiltration of pancreatic cancer cells into pancreatic islets via double-immunolabeling of human pancreatic cancer tissues with insulin or glucagon and the pancreatic cancer cell marker cytokeratin 19 (CK-19) or Mucin-1 (MUC1)." (PMID 33440856, 2021). "In the pancreatic cancer microenvironment, FAP-expressing CAFs have been a major source of CXCL12, which can bind to KRT19 (cytokeratin 19) at the surface of pancreatic cancer cells." (PMID 35805064, 2022). "For instance, in pancreatic tumors, the expression of SOX9 positively correlates with the expression of epithelial phenotype genes (CDH1, KRT7, KRT18, and KRT19) and negatively correlates with the expression of the mesenchymal phenotype gene VIM." (PMID 35884771, 2022). "Furthermore, five genes (KRT19, ALDOA, CLDN4, RAB27B, and GJB5) among the top 10 % coregulated genes were identified to have significantly elevated expression in pancreatic cancer compared to the normal pancreas." (PMID 40680814, 2025). "As expected, epithelial markers (Krt7, Krt8, Krt18, Krt19, Epcam, Egfr, Cdh1) were highly expressed in primary pancreatic tumors and in the cancer cell line NB508 and nearly absent in the nonepithelial MEFs and in normal WBCs." (PMID 25242334, 2014). "Based on the existing literature and our experimental results, we hypothesized that KRT7 and KRT19 are involved in EMT as epithelial components, while CXCL5 and IGF2BP3 act as regulatory factors to regulate EMT, thereby promoting the invasion and metastasis of pancreatic cancer." (PMID 37371833, 2023).
papillary thyroid carcinoma (41 papers, 2005 to 2026). "According to recent research, several diagnostic and prognostic markers have been proposed in improving the diagnostic accuracy of papillary thyroid cancer such as Cytokeratin-19 (CK-19), HBME-1, Galectin-3, CD44, CD56, E-cadherin, c-erbB-2, p21cip1, p27kip1, and p16ink4a." (PMID 21052476, 2010). "Cytokeratin-19 (CK-19) expression in thyroid nodules is in general intense and diffuse in papillary carcinoma and heterogeneous labeling in carcinoma and in follicular adenoma, with nil or low expression in other benign lesions." (PMID 22888980, 2012). "Cytokeratin 19 positivity was found in patients with papillary carcinoma, in one case of follicular adenoma, 3 multinodular goiters and one Basedow disease." (PMID 20565793, 2010). "First, we examined the expression of KRT19 in human thyroid follicular epithelial cells (Nthy-ori 3 − 1) and two human papillary thyroid carcinoma cells (TPC-1 and KTC-1) by Western Blot and further verified that KRT19 expression was significantly up-regulated in human PTC cells." (PMID 39453570, 2025). "Cytokeratin 19 (CK19) is part of the epithelial cytoskeleton, with tissue overexpression in differentiated thyroid carcinoma (DTC), particularly in cases of papillary carcinoma." (PMID 38828358, 2024). "In this context, the possibility that MFT–or at least some of its foci in a given case–may precede the development of papillary carcinoma is tantalizing and may be further supported by partial alteration of HBME-1, cytokeratin 19, Galectin-3, and CD56 expression patterns." (PMID 35819567, 2022). "The expression of Hector Battifora mesothelial epitope-1 (HBME-1) and cytokeratin 19 (CK19), and the absence of CD56 expression, are established immunohistochemical markers commonly found in papillary thyroid carcinoma." (PMID 40746588, 2025).
liver cancer (40 papers, 2003 to 2025). An epithelial or non-epithelial malignant neoplasm that arises from the liver. "Positivity for epithelial cell adhesion molecule (EpCAM) and cytokeratin-19 (CK-19) which are markers of liver cancer stem cells expressed in hepatic progenitor cells have been identified as poor prognostic factors for recurrence." (PMID 34638613, 2021). "However, even if the expression of gene KRT19 (target gene of CK19) can be measured by RNA-seq in 374 liver cancer samples from TCGA database to classify liver cancer into CK19-HCC and CK19+HCC, DPHCC cannot be subdivided further." (PMID 33854600, 2021). "We then confirmed that liver cancer organoids expressed liver cancer-specific characteristics by checking the expression of liver cancer differentiation markers (AFP and KRT19), proliferation marker (Ki67), and EMT activation markers (PDGFRB and α-SMA)." (PMID 40852642, 2025). "MYB- and HIF1α-co-regulated direct target, KRT19, exhibits positive correlation with HIF1α under hypoxia, while another target, ALDOA is shown to support hypoxic survival of liver cancer cells." (PMID 40680814, 2025). "The tumor cholangiocyte-like hepatocytes expressed KRT19 at higher levels than hepatocytes, as well as JARID2, which has been shown to be upregulated in liver cancers." (PMID 40766612, 2025). "We examined the liver cancer stem cell or progenitor markers (AFP, CD133, EPCAM, and KRT19), and hepatocyte terminal differentiation markers (ALB, G6PC, CYP3A4, and HNF4A) in subgroup of patients with different SOX signature scores." (PMID 31462277, 2019). "Among them, typical liver cancer stem cell markers such as AFP and keratin 19 (KRT19) were upregulated in FOXM1-high HCC, whereas typical mature hepatocyte markers such as solute carrier organic anion transporter family member 1B1 (SLCO1B1) and cytochrome P450 3A4 (CYP3A4) were downregulated." (PMID 35955438, 2022). "Intriguingly, the CCA marker KRT19 and the PROX1 targets PRRX1 and PPARG exhibited a negative correlation with PROX1 expression in tumor tissue, suggesting that PROX1 could regulate liver cancer plasticity and HCC versus CCA fate." (PMID 39948437, 2025). "Furthermore, Krt19 IHC highlighted a double population of cells with strong expression and adjacent zones with reduced expression, absent in the original transgenic YES1 Y537F liver cancer model from which HepYF-M13 cells were derived." (PMID 39051113, 2024).
liver fibrosis (37 papers, 2017 to 2026). "To understand the role of cholangiocytic Prom1 in liver fibrosis, we generated cholangiocyte-specific Prom1-deficient mice (Prom1f/f; Krt19-Cre) by crossing Prom1f/f mice (f/f) with transgenic Krt19-Cre mice." (PMID 36038590, 2022). "After 12 weeks, cells in the biliary epithelium co-expressed both α-SMA and cytokeratin-19, a biliary epithelium marker, while also actively producing collagen I, indicating that epithelial to myofibroblast transition play a role in liver fibrosis." (PMID 41511495, 2026). "We analyzed liver fibrosis in Prom1f/f(f/f) and Prom1f/f; Krt19-Cre (f/f; Krt19-Cre) mice after BDL." (PMID 36038590, 2022). "Cont-SHED represented in vivo bile drainage function and KRT19-positive biliary regeneration in chronic carbon tetrachloride-induced liver fibrosis model mice." (PMID 34809720, 2021). "The mRNA levels of liver fibrosis markers (Acta2, Col1a1, Col3a1, and Timp1), cholangiocyte proliferation markers (Krt7 and Krt19), inflammation markers (Il6 and Il1b), and the progenitor cell marker (Sox9) were markedly decreased in miR-200c-BDL mice compared to con-BDL mice." (PMID 34880414, 2022). "Specifically, 680 proteins in cluster 1, including pro- and anti-inflammatory cytokines (e.g., IL-6 and IL-10) and liver fibrosis markers (e.g., ACTA2, KRT19, and SPP1), increased progressively with fibrosis stages." (PMID 39889710, 2025). "Transcriptional levels of liver fibrosis markers (ACTA2, COL1A1, COL1A2, COL3A1) and ductular reaction markers (EPCAM, KRT7, KRT19) were significantly upregulated in BA." (PMID 36816373, 2023). "The validation cohort showed GPC3 was negatively correlated with all liver fibrosis markers ACTA2, COL1A1, COL1A2, COL3A1 and ductular reaction markers KRT7 and KRT19, while SDC4 was positively correlated with ductular reaction index KRT19." (PMID 36816373, 2023). "Liver SCTR expression localized in cholangiocytes and correlated positively with liver fibrosis, DR, and transcriptional markers of fibrosis (ACTA2) and cholangiocytes (KRT7, KRT19) both at PE and after SPE." (PMID 35508528, 2022). "After silencing and overexpression of GLI1/GLI2, immunofluorescence was used to detect the expression of cytokeratin-19 (CK19) and α-smooth muscle actin (α-SMA) in mIBECs, and hematoxylin and eosin (HE) staining and Masson staining were used to observe the degree of liver fibrosis in the BA animals." (PMID 35692978, 2022). "Cytokeratin 19 (CK19) is expressed normally in the lining of hepatobiliary tracts and considered as a helpful marker for the occurrence of ductular reaction which is closely related to liver fibrosis and damage." (PMID 35648193, 2022). "Liver fibrosis and intrahepatic bile duct reaction, measured by Sirius red staining, Western blots of α–smooth muscle actin (α-SMA) and collagen 1, and cytokeratin 19 (CK19) immunostaining, were significantly increased by BDL to a greater extent in KO mice than WT mice." (PMID 32701506, 2020).
squamous cell carcinoma (37 papers, 2006 to 2025). A carcinoma arising from squamous epithelial cells. "In addition, serum tumor markers including carcinoembryonic antigen (CEA), cyfra (cytokeratin 19 fragment), squamous cell carcinoma (SCC), and CA72-4 (tumor-associated glycoprotein 72) were tested in 12 of the patients preoperatively, yet none presented positive results." (PMID 27033424, 2016). "Sialylated Lewis X antigen, cytokeratin 19 fragment, and soluble interleukin-2 receptor were tested for suspected adenocarcinoma, squamous cell carcinoma, and lymphoma, respectively." (PMID 41001313, 2025). "For example, downregulation of keratin 19 has been shown to influence the invasive phenotype of several squamous cell carcinoma cell lines, including those derived from the oral epithelium." (PMID 41009656, 2025). "An increased expression of HB marker keratin 19 (K19) has been observed in human squamous cell carcinomas (SCCs), whereas basal cell carcinomas and trichoblastomas were shown to up-regulate the expression of the HB marker keratin 15 (K15)." (PMID 32423907, 2020). "Head and neck tumours are squamous cell carcinomas and expression of KRT19 is a poor prognostic marker." (PMID 31331335, 2019). "Previous studies using immunohistochemical analysis for resected adenocarcinoma and squamous cell carcinoma, showed that cytokeratin-19, the marker used for CYFRA21-1, stained both adenocarcinoma and squamous cell carcinoma strongly and indiscriminately." (PMID 22954172, 2012). "KRT19 mRNA has also been reported to be downregulated in squamous cell carcinoma (SCC) of the head and neck and the over-expression of the gene was shown to decrease SCC invasiveness by diminishing migratory capability." (PMID 21314941, 2011). "Furthermore, most of them showed high expression levels of KRT19 mRNA except one adenocarcinoma and one epidermoid carcinoma." (PMID 31331335, 2019). "Cytokeratin 19 (CK19), a cytoskeletal protein, is specifically expressed in epithelial cells and their derived malignancies such as squamous cell carcinoma (SCC)." (PMID 40746926, 2025). "As KRT19 was overexpressed in adenocarcinoma (AC) and squamous cell carcinoma (SCC), we examined the prognostic value of KRT19 protein abundance by tissue microarray (TMA)." (PMID 33442422, 2021). "Currently, carcinoembryonic antigen (CEA), neuron-specific enolase (NSE), cytokeratin 19 fragment (CYFRA21-1), pro-gastrin-releasing peptide (ProGRP) and squamous cell carcinoma (SCC) antigen are commonly used markers for the diagnosis of lung cancer." (PMID 34785692, 2021). "Our findings revealed significant immunopositivity for Cytokeratin 8/18 (CK8/18) and Cytokeratin 19 (CK19) in NK-NPC cases compared to benign controls (p < 0.001), supporting our hypothesis based on data from squamous cell carcinomas at other anatomical sites." (PMID 41008664, 2025). "A previous study showed high expression levels of KRT7 and KRT19 in Cervical Intraepitelial Neoplasm grade 3 (CIN3) and squamous cell carcinoma (SCC), supporting the idea that KRT19 may promote E7 oncoprotein production, contributing carcinogenic events." (PMID 32337254, 2020). "In addition, the associations between the level of carcinoembryonic antigen (CEA) and frequency of Th22 cells in patients with AC and between the level of cytokeratin-19-fragment (CYFRA21-1) and frequency of Th22 cells in patients with squamous cell carcinoma (SCC) were, respectively, analyzed." (PMID 35669104, 2022).
lymph node metastasis (34 papers, 2005 to 2025). "One-step nucleic acid amplification (OSNA) for cytokeratin 19 messenger RNA is an intraoperative diagnostic procedure for the detection of lymph node metastasis." (PMID 29978372, 2018). "Expression of MMP-2 and cytokeratin 19 are independent risk factors for prediction of lymph node metastasis and survival." (PMID 26472188, 2015). "One-step nucleic acid amplification (OSNA) is another method for lymph node metastasis assessment, that is progressively being applied intraoperatively, detecting and quantifying the cytokeratin-19 (CK-19) mRNA, providing accurate and consistent results." (PMID 34771500, 2021). "Previous our study showed the usefulness of the reverse transcription loop-mediated isothermal amplification (RT-LAMP) targeting keratin 19 (KRT19) mRNA for the genetic detection of lymph node metastasis, but the sensitivity was insufficient." (PMID 26700817, 2016). "A new diagnostic system, called one-step nucleic acid amplification (OSNA), has recently been designed to detect cytokeratin 19 mRNA as a surrogate for lymph node metastases." (PMID 22684906, 2012). "The one-step nucleic acid amplification (OSNA) assay (Sysmex Corporation) is a rapid molecular detection procedure that analyses lymph-node metastases by detection and amplification of cytokeratin 19 (CK19) mRNA." (PMID 21878934, 2011). "The OSNA assay, a new method developed in 2007, measures the tumor cell-specific expression of cytokeratin 19 (CK19) mRNA in lymph nodes and determines the presence of lymph node metastasis by comparing the level to a cut-off value." (PMID 35312731, 2022).